TNF (tumor necrosis factor)
Diseases named in the same sentence as TNF in open-access papers (continued):
Sharing a sentence is not in itself a finding about the gene and the disease.
cancer (continued). "TNF is interconnected with ROS, dysregulation of which is a hallmark of cancers and inflammatory diseases." (PMID 34122086, 2021). "Thirdly, many cancer cells exhibit deficiencies in normal antiviral interferon (IFN) or tumor necrosis factor (TNF) responses which encourage selective virus replication." (PMID 35004328, 2021). "The storm of cancer-induced inflammatory cytokines, in particular TNF-α, is a crucial pathogenic mechanism." (PMID 34900737, 2021). "TNF-α and IL-6 are both pleiotropic cytokines playing major roles in cancer-associated cytokine networks." (PMID 33461943, 2021). "Several studies have reported that cytokines such as IL-6, IL-8, IL-10, TGF-β, and TNF-α are detected in cancer-associated exosomes, leading to cancer progression and drug resistance." (PMID 34771423, 2021). "An earlier study that evaluated the association between proinflammatory cytokines and cancer incidence revealed that IL-1β, IL-6, and TNF-α are associated with an increased risk of cancer." (PMID 33869169, 2021). "Unfortunately, there are currently no human data available that demonstrate a clear effect of anti-TNF antibodies in protection from IBD-associated cancer." (PMID 34884543, 2021). "TME-mediated growth factor receptors, chemokines (CCL2, CCL5), and cytokines (IL-1β, IL-6, TNFα) are associated with aggressiveness of cancers and poor prognosis of patients." (PMID 34948368, 2021). "Cancer-associated inflammation is mediated by infiltration of leukocytes and secretion of various cytokines such as TNF-α, IL-6, IL-8, TGF-β1, and IL-10." (PMID 34778599, 2021). "Previous studies have shown that TNFα synergistically enhances the apoptotic susceptibility of HCC cells to commonly used anti-cancer drugs like Taxol (Paclitaxel)." (PMID 34869307, 2021). "In contrast to its role in inflammation, in cancer, TNF deficiency decreases the susceptibility of tumors to immunotherapy, whereas TNF blockade reduces colorectal carcinogenesis." (PMID 33578830, 2021). "These upregulated PRC2+-CGI genes control important pathways such as Epithelial-Mesenchymal Transition (EMT) and TNFα-associated inflammatory response, and have greater cancer-type specificity than other CGI genes." (PMID 33931649, 2021). "The first inflammatory cytokine to be linked to cancer cachexia was the tumor necrosis factor (TNF), also known as cachectin, due to its elevation in the blood of cachectic cancer patients and its capacity to induce muscle wasting in animal models." (PMID 33419963, 2021). "For cancer-immunity cycles, TNF-based risk score was significantly positively correlated with the majority of these seven steps, including T-cell recruiting, CD8 T-cell recruiting, macrophage recruiting, TH1 cell recruiting, and killing of cancer cells (left)." (PMID 35174161, 2021). "Although the association of IFNγ signaling as a single variable with cancer recurrence was more significant than that of TNFα signaling, the combined effects of TNFα/TGFβ signaling were more significant than combination of IFNγ/TGFβ signaling in BLBC." (PMID 33767579, 2021). "In the present investigation, this finding revealed that P. freyniana possessed 43 flavonoids (40 of them was first reported) with 23 core target genes, which were associated with PI3K-Akt, MAPK, TNF signaling pathway, and pathway in cancer." (PMID 33574846, 2021). "Regarding TNF-α 308G/A gene polymorphism in the NSCL cancer group, the heterozygous GA genotype was frequently detected in patients of the cachectic group, followed by the homozygous AA genotype with the least percent carrying the homozygous GG genotype." (PMID 34900737, 2021). "Knockout of miR-146a leads to excessive production of inflammatory cytokines such as TNF-α and IL-6, which, in turn, induces chronic inflammation and increases susceptibility to cancer and loss of Treg cell function." (PMID 34790566, 2021).
cancer (continued). "P. freyniana possessed 43 flavonoids (40 of them was first reported) with 23 core target genes, which are associated with PI3K-Akt, MAPK, TNF signaling pathway, and pathway in cancer." (PMID 33574846, 2021). "TNF-α and myostatin play important roles in muscle atrophy associated with cancer cachexia and various chronic diseases." (PMID 32267872, 2020). "The results also shed new light on the molecular mechanism underlying TNFα-promotion of cancer cells apoptosis induced by some anticancer drugs such as DOX." (PMID 32225068, 2020). "A high level of TNF-α is associated with aggressive behavior and poor prognosis in many malignant cancers." (PMID 32592356, 2020). "This study found evidence of causal associations of increased TNF levels with higher risk of common cardiovascular diseases and lower risk of overall and certain cancers." (PMID 32805626, 2020). "Third, inflammatory markers such as IL6, IL8, CRP, and TNFα are associated with fatigue in cancer survivors." (PMID 33317113, 2020). "We conducted a two-sample Mendelian randomization study to explore the associations of genetically predicted TNF levels with risk of 14 CVDs, overall cancer, and 14 site-specific cancers." (PMID 32805626, 2020). "Simulating the inflammation in a tumor environment, TNF-α treatment of a microvessel network also caused HUVEC layer permeability resulting in a 2.3-fold increase of cancer transmigration rate." (PMID 33585411, 2020). "Cancer-associated adipocytes interact with cancer cells and secrete the inflammatory cytokines, such as IL-6 and TNF-α, which contribute to pro-cancer inflammation that is known to aggravate cancer progression." (PMID 32796516, 2020). "As well, we identified several proinflammatory cytokines such as IL-1 alpha, IL4, IL6, LIF, TNF which have been implicated in cancer cachexia." (PMID 33334063, 2020). "This is supported by GSEA results that showed significant up-regulation of a number of cancer- and early development-associated pathways (e.g. INFα, TNFα, Jak-STAT and Wnt/beta catenin)." (PMID 32520939, 2020). "Pro-inflammatory cytokines including tumor necrosis factor α (TNFα) and interleukins 1, 6, and 10 (IL-1, IL-6 and IL-10) have been associated with the cachectic phenotype in several cancer models." (PMID 32605273, 2020). "The role of TNF-α is important in cancer development therefore common functional polymorphisms (rs1800629 and rs361525) have been examined extensively in many studies." (PMID 32102503, 2020). "The RNAseq results suggested that TEX10 is associated with several cancer‐related signal pathways, such as TNF signaling, EMT, and hypoxia." (PMID 32995120, 2020). "Some studies have indicated that TNF-α plays an essential role in connecting the molecules associated with inflammation and cancer." (PMID 32802118, 2020). "Pro-inflammatory cytokines such as tumor necrosis factor (TNF)-α have been implicated in muscle atrophy related to cancer cachexia or aging." (PMID 32398756, 2020). "TNF-α affects not only cell growth, differentiation, and function but also causes genetic mutations promoting cancer development, and modulates the expression of inflammatory genes." (PMID 32230772, 2020). "Enrichment analysis revealed that they were significantly enriched in several cancer-associated pathways, such as cell cycle, TNF signaling pathway, Jak-STAT signaling pathway, and NF-kappa B signaling pathway." (PMID 32500028, 2020). "TNFα is considered one of the most important inflammatory mediators of the cancer-associated inflammatory networks." (PMID 32256215, 2020). "This network was composed of central functional components associated with metabolism and cancer such as TNF, MAPK, TRIM21 and one component contained APP." (PMID 32228434, 2020).
cancer (continued). "This study first showed that the TNF-α H-score was associated with cancer relapse in patients with cervical AC." (PMID 32527042, 2020). "Overall, cytokines are divided into proinflammatory groups such as TNF-α, IL-1β, IL-2, and IL-6, which play a role in initiating chronic inflammation and activating the NF-κB pathway and are strongly linked to cancer growth." (PMID 32156252, 2020). "In support of the notion that inflammation-activated or dysfunctional vasculature occurs in cancer progression, circulating levels IL-6 and TNF-α have been correlated with the risk of developing cancer, and with increased cancer deaths among older adults." (PMID 31656195, 2019). "At the same time, Bifidobacterium can inhibit the growth of spoilage bacteria and decompose carcinogens to achieve anti-cancer effects and reduce the inflammation caused by TNF-α and lipopolysaccharide." (PMID 31065547, 2019). "Numerous studies have reported that the concentration of circulating TNF cytokines is increased in some cancer patients and has been linked to progression of malignancy." (PMID 31231550, 2019). "The -308G/A polymorphism of TNF-α has been widely investigated in relation to various diseases, including infectious diseases and cancers." (PMID 30600678, 2019). "Several inflammatory cytokines are upregulated in cancer tissue, including tumor necrosis factor alpha (TNF-α), a potent cytokine that causes necrosis and inflammation and promotes cancer." (PMID 30999696, 2019). "Non-steroidal anti-inflammatory drugs including aspirin have been found to inhibit TNF-α, NF-κB, and Wnt/β-catenin signaling pathway and to reduce the risk of cancer." (PMID 30740360, 2019). "Additional pathways included Notch, Hippo, TNF and Rap1 signaling, as well as cancer-associated regulation pathways." (PMID 31740700, 2019). "The main cause of the reduction of the albumin level, especially in cancer patients, is the inhibition of albumin-regulating gene by tumor necrosis factor which results in mRNA expression reduction of approximately 90% in the liver." (PMID 31294654, 2019). "In one of the cases, we noted that a TNF-α mRNA positive cancer cell was often associated with miR-21 in neighboring cancer cells and stromal cells." (PMID 30999696, 2019). "High levels of TNFα causes chronic inflammation and insulin resistance, that in turn provides positive effects on the development of cancers." (PMID 31398937, 2019). "Among these, tumor necrosis factor alpha (TNFα) plays a relevant role in enhancing cancer risk, cancer growth, and cancer-associated cachexia." (PMID 30764482, 2019). "A large number of studies have indicated that TNF-α displays a degree of potential in linking the molecules associated with inflammation and cancer." (PMID 31540489, 2019). "Recently, high serum levels of IL-1β, IL-6, IL-8, and TNF-α in cancer patients have been linked to CC pathogenesis." (PMID 30513776, 2018). "Until today, several polymorphic variants of TNF-α have been described in literature as unfavorable factors responsible for intensification of cancer related inflammatory response." (PMID 29802455, 2018). "Further evidence is needed pertaining to cancer risk in patients who are using, or have used, anti-TNFα agents." (PMID 29954352, 2018). "One of the key chemical mediators implicated in inflammation-associated cancers is TNF-α which leads to activation of the NF-κB and AP-1 transcription factor complexes." (PMID 29593647, 2018). "PubMed, Web of Science, Embase, Wanfang database, VIP database, and China National Knowledge Infrastructure database were used to obtain articles on association between TNF-α-308G>A polymorphism and cancer survival, published until April 2018." (PMID 30407345, 2018).
cancer (continued). "This meta-analysis aimed to determine the correlation between TNF-α-308G>A polymorphism and the survival of cancer patients." (PMID 30407345, 2018). "Those substances are mainly inflammatory mediators like tumor necrosis factor alpha (TNF-α), and are linked to cancer initiation." (PMID 30012980, 2018). "In total, 13 retrospective cohort studies including 2559 cancer patients were reviewed to estimate the association between TNF-α-308G>A polymorphism and overall survival (OS) of cancer patients." (PMID 30407345, 2018). "Despite this study being the first comprehensive meta-analysis on the association between TNF-α-308G>A polymorphism and cancer prognosis, this meta-analysis has some limitations." (PMID 30407345, 2018). "In contrast to TNF-α, circulating levels of IL-6 have been shown to correlate with weight loss in cancer patients, and importantly, IL-6 levels correlated with reduced survival." (PMID 29338749, 2018). "Particularly, CRP, IL-6 and TNF-α, in particular, have been reported to be associated with a variety of cancers." (PMID 29844870, 2018). "Catabolic pro-inflammatory cytokines associated with cancer cachexia include interleukin-6 (IL-6), interleukin-1 beta (IL-1B), tumor necrosis factor alpha (TNF-α), and interferon gamma (IFN-γ)." (PMID 30591621, 2018). "Summary of primary data for association between TNF-α-308G>A polymorphism and overall survival of cancer from 13 eligible studies." (PMID 30407345, 2018). "After 2 days of co-culture, monocytes exposed to cancer cell lines showed markedly upregulated expression of M1-associated (TNF-α, IL-1β), M2-associated (CCL13, CD206), Mreg-associated (IL-10, TGF-β), and angiogenesis associated (MMP9, VEGF) genes." (PMID 29668679, 2018). "Protein factors/bio-molecules which are associated with the neutralization of TNFα-mediated inflammation and apoptosis play an important role in the treatment of cancer because of their association with drug resistance." (PMID 30586922, 2018). "Among potential molecular alterations related to cancer cachexia, there are single-nucleotide polymorphisms (SNPs) within genes encoding pro-inflammatory cytokines such as TNF-α." (PMID 29802455, 2018). "Up until now, several functional single-nucleotide polymorphisms (SNPs) within TNF-α gene have been identified and described as cancer related genetic alterations." (PMID 29802455, 2018). "TNF-α-308G>A polymorphism affects the OS of cancer patients and is a potential therapeutic target for cancer." (PMID 30407345, 2018). "M1 macrophages are activated by LPS, IFN-γ, and TNF-α, and are associated with the expression of cytokines such as IL-1β, IL-6, IL-9, IL-13, and inducible nitric oxide synthase (iNOS) in cancer patients." (PMID 30060484, 2018). "Key inflammatory mediators, such as (interleukin 1 (IL-1), IL-6, and TNF-α) are also implicated in carcinogenesis as well as in established cancer biology processes." (PMID 29587429, 2018). "In conclusion, our study suggests the prediction role of TNF-α-308G>A polymorphism in cancer patient survival." (PMID 30407345, 2018). "This study is the first, to our knowledge, comprehensive meta-analysis of available studies for global analysis of an association between TNF-α-308 polymorphism and overall survival of cancer patients." (PMID 30407345, 2018). "As TNF is a key player in the cytokine network that supports inflammation-associated cancer and cancer-related inflammation, it will be important to gain a better understanding of the checkpoints that control life and death decisions in response to TNF." (PMID 29452637, 2018). "In CRC patients who had undergone surgery for their primary cancer, the higher levels of TNF-α were specifically associated with CRC-specific mortality." (PMID 29949857, 2018). "SSd enhances TNF-α-mediated apoptosis by suppressing TNF-α-induced NF-κB activation and the expression of its target prosurvival genes implicated in cancer cell proliferation, invasion, angiogenesis, and metastasis." (PMID 29849917, 2018).
cancer (continued). "We also tried to analyze the association between TNF-α-308 genotypes and OS of patients with specific types of cancer." (PMID 30407345, 2018). "To provide new tools for cancer immunotherapy, we developed two rSFV vectors that encoded either murine TNF-α or IFN-γ and tested the functionality of the resulting rSFV-encoded cytokines in vitro." (PMID 29276511, 2017). "The rSFV inhibited LLC cell growth, induced cancer cell death and simultaneously exploited cancer cells for production of SFV-encoded TNF-α and IFN-γ at levels that are functional in vitro." (PMID 29276511, 2017). "Cancer is associated with inflammation and some of the inflammatory markers such as TNF-α, IL1, IL-6 become increased in HCC and after DEN administration, as both are associated with inflammation." (PMID 28830415, 2017). "Tumour necrosis factor-α (TNF-α) is a double-edged cytokine associated with pathogenesis of inflammatory-related cancers being also able to induce cancer cell death." (PMID 28149533, 2017). "Single nucleotide polymorphisms in TNF-α gene is reportedly associated with the cancer diagnosis, treatment outcome, and survival of cancer patients." (PMID 28575042, 2017). "TNF-α can heighten the expression of CXCL1/2 in cancer cells, thus amplifying the CXCL1/2-S100A8/9 loop and causing chemo-resistance." (PMID 29245915, 2017). "Several of these cytokines, including TNF-α, IL-1, and IL-6, have themselves been shown to have an association with worse prognosis in patients with cancer." (PMID 28239396, 2017). "Cytokines such as tumor necrosis factor-α, interleukin-1, IL-6, and IL-18; oxygen free radicals; and nitrogen-based biological effectors have all been implicated in promoting cancer cell growth." (PMID 28284210, 2017). "Constitutive TNF-α production is a characteristic for many malignant tumors, and linked to all steps of tumorigenesis in many cancer types." (PMID 28107185, 2017). "Although, this was highest for the DMARD group (57%), excluding ‘theoretical increased risk from cancer’ from analysis, the anti-TNF groups performed at a similar level (55 and 62%, respectively)." (PMID 28526972, 2017). "TNF-α -1031 polymorphism has been investigated in several cancers, autoimmune diseases, hepatitis, and infectious diseases." (PMID 29118938, 2017). "Inflammatory cytokines such as IL-6, CRP, and TNF-alpha have been shown to be associated with cancer incidence." (PMID 29045425, 2017). "The tumor necrosis factor (TNF) and interleukins 1 and 6 (IL-1 and IL-6) proinflammatory cytokines cause multifactorial disease such as cancer and systemic inflammations." (PMID 28400756, 2017). "Pro-inflammatory cytokines, such as IL-1, IL-6 and TNF-α, are associated with colitis-associated cancer." (PMID 29285251, 2017). "The failed anti-TNF patients were less concerned about potential increased risk from cancer (p = 0.037)." (PMID 28526972, 2017). "Inflammation is additionally linked to cancer development, and increased levels of TNF-α, IL-6, selectins, and leptin and decreased levels of adiponectin are associated with enhanced metastasis and increased risk of several cancers." (PMID 28185008, 2017). "Biological vehicles have been examined for this purpose in the context of cancer gene therapy, and TNFα delivery by viruses such as adeno-associated virus or adenoviruses have shown promise." (PMID 28662099, 2017). "Collectively, these data suggested that triggering autocrine TNF production via hypertonicity-induced p38/NFAT5 activation was underlying synergistic cancer cell killing of SM/NaCl combinations." (PMID 28771230, 2017).